CD38 (CD38 molecule)
Diseases named in the same sentence as CD38 in open-access papers (continued):
Sharing a sentence is not in itself a finding about the gene and the disease.
tumor (continued). "As CD38 has broad expression in peripheral blood, we hypothesized that the proximity between the anti-CD3ε and anti-CD38 domains may trigger CD38+-cell depletion and higher T cell activation in the absence of tumor cells." (PMID 39261676, 2024). "This was in turn validated molecularly on CD38 IHC wherein comparison to diffuse strong membranous positivity of CD38 in all the marrow cells of the vehicle tumor tissue, we saw near total absence of CD38 in any remnant cells in the AU-24118-treated orthotopic xenografts." (PMID 38328238, 2024). "CD38's role in the production of the immunosuppressive molecule adenosine, via the CD38/CD203a/CD73 extracellular enzyme pathway, further modulates immune responses by binding to adenosine receptors on CD8 T cells, inhibiting their proliferation and facilitating tumor immune escape." (PMID 39492834, 2024). "This was inturn validated molecularly with CD38 IHC, where, in comparison to diffuse strongmembranous positivity of CD38 in all marrow cells of the vehicle tumor tissue,there was near total absence of CD38 in any remnant cells in theAU-24118-treated orthotopic xenografts." (PMID 39029462, 2024). "Since CD38 expression was increased by cisplatin or etoposide on SCLC cells in vitro, the direct blockade of CD38 on tumor cells starting early timing might suppress the tumor growth." (PMID 38533509, 2024). "However, additional tumor targets such as CD20, CD30, CD38, and CD138 have also been investigated." (PMID 37420216, 2023). "Although these small molecule inhibitors of CD38 have not been reported in the literature for their use in tumor treatment, we strongly believe that these inhibitors will at least become powerful tools for unveiling the role of the enzymatic function of CD38 in tumors and solid TME." (PMID 38116009, 2023). "Therefore, it still needs to be clarified whether the CD38 monoclonal antibody leads to an increase in the intracellular NAD+ level and whether it plays a double-edged sword role in tumor treatment." (PMID 38116009, 2023). "Importantly, in the BR baseline group compared to the similar GR group, there was a higher tumor burden with high expression of classical MM markers, namely, CD38 and CD56 (NCAM), accompanied by the absence of CD45 expression." (PMID 37174069, 2023). "However, targeting of either CD38 or Ntrk1 was not curative in KP lung tumor models, suggesting that additional mechanisms can drive tumor cell survival in the face of ICB." (PMID 37655662, 2023). "Although CD38 expression increases during B cell differentiation to ASC precursors, its downregulation during ASC maturation was unanticipated; however, this feature may actually be consistent with enhanced survival in tumor cells." (PMID 37355988, 2023). "Thus, optimal timing of 225Ac CD38-TAT was at the point of tumor regrowth when CS1 CAR T cell therapy was no longer effective." (PMID 37209218, 2023). "In addition, the numbers and expression of CD38+ MDSC were diminished by PD-1 antibody compared to IgG2a treatment in tumor-bearing Shp2f/f mice, but not in Shp2f/fLysMCre mice." (PMID 36581713, 2023). "Although, our study focuses on understanding the immune corelates of BCG responsiveness, we propose that the enrichment of PD1+CD38+Tim3+ CD8+ T cells at the NMIBC tumor site is not solely related to BCG response, rather it stratifies patients with a high recurrence risk already at the baseline." (PMID 37566017, 2023). "Importantly, the combination of the CD38 antibody and CD20-directed bibodies [CD20×NKG2D#3] or [CD20×NKG2D#32] was, with 33.0% and 45.2%, significantly more effective in triggering effector cell killing of tumor cells than the single agents." (PMID 37965326, 2023). "Thirdly, the CD38-daratumumab complex is shown to be transferred from MM cells to monocytes and granulocytes in a process known as trogocytosis, even with the absence of phagocytosis of tumor cells." (PMID 36139103, 2022).
tumor (continued). "However, profound preclinical and clinical data are required to safely conclude that CD38 targeting via nanobody-based CAR-Ts does not mediate off-tumor cytotoxicity against T cells, B cells, and NK cells proficient in the expression of CD38." (PMID 35468841, 2022). "Moreover, the increased expression of PD-1 in CD38+ CD8+ T cells compared with CD38− CD+ T cells was only observed in tumor, but not in peripheral blood and normal tissues." (PMID 33934206, 2021). "And administration of 8-Br-cADPR (a competitive CD38 enzyme hydrolysate inhibitor) could result in a significant inhibition of cell proliferation, colony formation, and migration on CD38 WT and OE tumor cells, but not on CD38 KO and MU cells." (PMID 34226519, 2021). "CD38 CAR-T cells could be activated by CD38-positive tumor cells but not by tumor cells that do not express CD38, which further confirms the killing specificity of this kind of CD38 CAR-T cell." (PMID 34513682, 2021). "Additionally, we found that the proportions of total plasma cells (CD19+ CD20+ CD27+ CD38+) and of those secreting IgG and IgM in PDAC were significantly lower than those in the healthy donors, which gradually decreased in higher tumor stages." (PMID 34359579, 2021). "In that context, we do not consider tumor CD11b+/CD38+ cells as M1 macrophages." (PMID 34835178, 2021). "BiTEs and hemibodies were next tested in T cell cultures in the absence of tumor cells, because we detected the substantial expression of CD38 and SLAMF7 on CD3 and CD8 T lymphocytes, albeit distinct T cell subpopulations expressed the antigens in a mutually exclusive pattern." (PMID 33420283, 2021). "In contrast, the combination of anti-CD38 antibody, L82-pulsed DC vaccine, and CpG suppressed LLC1 tumor growth (p = 0.019), although neither anti-CD38 mAb nor L82-pulsed DC monotherapy alone could do so." (PMID 34771674, 2021). "Taken together, CD8Low ST2L+ T lymphocytes exhibited higher protein expression of CD38 and CD39, whereas PD-1 expression dominated on CD8High ST2L+ T lymphocytes, potentially limiting the cytotoxic effector functions of CD8+ T lymphocytes and thereby presumably promoting a tumor-supporting milieu." (PMID 34504486, 2021). "Apart from CD38, SARM1 were also confirmed as the additional NAD+-depleting enzyme that using NAD+ to produce cADPR, the precise functions of cADPR in those abnormal situations including tumor progression, inflammation, and injury-induced axon death need further characterizations." (PMID 34226519, 2021). "Consistent with the literature report that, despite the different levels of CD38 expression, antibody 028 could not distinguish tumor cells from normal cells." (PMID 33747727, 2021). "Importantly, neither BCMA-CAR nor CD38-CAR-transduced iNKT cells displayed any significant off-tumor toxicity toward normal hematopoietic cells." (PMID 33499253, 2021). "It has been described that TCR-activated Cd38−/− CD4+ T cells show a hybrid Th1/Th17 phenotype exhibiting intrinsically higher NAD+, enhanced oxidative phosphorylation, higher glutaminolysis, and altered mitochondrial dynamics that vastly improved tumor control." (PMID 34504495, 2021). "Moreover, CD38 expression was positive correlated with infiltrating levels of B cells, CD8+ T cells, CD4+ T cells, macrophages, neutrophils and dendritic cells in LUAD and LUSC, but negatively related to tumor purity." (PMID 33934206, 2021). "Memory-like NK cells derived from both haplo-HSCT donors and cancer patients also display some adhesion/homing surface antigens such as CD38, CD18, CD49D, CD62L and CXCR4, which could favor their proliferative and migration capacity and have a role in mediating cytotoxicity against tumor cells." (PMID 33808051, 2021). "Importantly, the CD38-targeted nanoparticles showed 2.6-fold increase in tumor accumulation over that of the nontargeted nanoparticles and a 4.2-fold increase over the free drug." (PMID 33138841, 2020).
tumor (continued). "Although the currently available BCMA/CD38 bispecific CAR T cell therapy has shown a similar safety profile as seen in BCMA directed products without any unexpected events, on-target off-tumor toxicity and fratricide cytotoxicity should be taken into account when targeting CD38 with CAR T cells." (PMID 33424871, 2020). "In 2009, we proposed CD38 as an MM target in virtue of its expression: Absent on early hematological progenitors, variable but generalized limited expression by normal cells, but extremely high in plasma cells and on their tumor counterpart MM." (PMID 33096610, 2020). "In addition, expression of TNFR2+ in the CD38+HLA-DR+CD8+ T-cell population appeared to be tumor specific, as these cells were not significantly potentiated in the patient PBMCs." (PMID 31649684, 2019). "Genetic and proteomic analyses revealed that CD38 is upregulated in response to a re-invigorated immune response resulting from treatment with PD(L)-1 blocking antibodies, namely through all-trans retinoic acid (ATRA) and a type I interferon response within the tumor." (PMID 31878283, 2019). "Although the tumor cells were negative for CD38 and CD138, the diagnosis of PBL was still rendered." (PMID 31565447, 2019). "Our data suggest that CD56bright NK cells may have a negative effect on the anti-tumour response by inhibiting T cell responses, via CD38, perforin, CD11a and IFNγ." (PMID 30872676, 2019). "In addition, daratumumab-mediated reduction of CD38 on MM cells may also decrease the generation of immunosuppressive ADO molecules, which would result in an improved host-anti-tumor immune response." (PMID 31068926, 2019). "Furthermore, it was recently shown that CD38 is highly expressed by specific subsets of immunosuppressive TILs (i.e., Treg and Th17) and by MDSC, another key immunosuppressive cellular component of tumor milieu represented." (PMID 31402913, 2019). "However, the receptor function of CD38 was not fully explored in this model, nor was the expression of CD38 on immune subpopulations within the tumor." (PMID 31878283, 2019). "Reflecting the important role of ADO in the tumor context, CD39, CD73, and CD38 ectoenzymes have been identified as potential biomarkers for clinical outcomes in chemo- and immune-therapies and to identify immune subsets that may be responsible for immunosuppression or are in an exhausted state." (PMID 30513816, 2018). "In addition to anti-CD20 Abs, other approved C-fixing Abs directed against various tumor antigens have been recognized to activate C both in vitro and in vivo including anti-CD52 alemtuzumab, anti-CD38 daratumumab, anti-EGFR cetuximab, anti-GD2 dinutuximab and anti-HER2 pertuzumab." (PMID 30319647, 2018). "Furthermore, this antibody combination is also tested in other tumors irrespective of expression of CD38 on the tumor cells." (PMID 30294326, 2018). "Since they were mononuclear cells present in tumor microenvironment, mainly in stroma, we conducted immunofluorescence staining using markers for mast cells (mast cell tryptase), macrophages (CD68), plasma cells (CD38), T- and B- lymphocytes (CD3, CD20 and CD79a) and neutrophils (NE)." (PMID 29543850, 2018). "Thus, anti-CD38-IFNα(att) exhibited negligible IFNα activity on normal, CD38 negative cells while retaining strong anti-tumor activity on CD38 positive tumor cells." (PMID 27611189, 2016). "The CD38 antibody portion of the immunocytokine would, however, direct a high local concentration of attenuated IFNα to the surface of CD38 positive tumor cells (upper diagram), thereby compensating for the weakened binding of IFNα to IFNAR and restoring activity on the targeted tumor cells." (PMID 27611189, 2016). "The finding that perforin migration towards the synapse requires CD38 as well suggests that both CD38 and TRPM2 are absolutely essential for the migration of perforin (or possibly cytolytic granules as well) toward the immunological synapse when NK cells encounter tumor cells." (PMID 25879940, 2015).
tumor (continued). "However, the proposed function of CD38 as an adhesion molecule is not likely, as evidenced by the lack of difference in the formation of conjugates between the tumor and Cd38+/+ and Cd38−/− NK cells." (PMID 25879940, 2015). "The tumor cells were observed to be negative for CD38 and CD138." (PMID 25013515, 2014). "Precise identification of Tregs will allow a better comparison of their levels to potentially beneficial subsets (for tumour elimination) such as CD4 effector (CD25int) or CD8 central and effector memory T cells, particularly for those that have been activated in the patients (CD38+)." (PMID 24213326, 2012). "The depth of response somewhat aligned, but was not directly correlated, with tumor CD38 expression levels in vitro, though we do acknowledge that levels of target expression on cell lines may not necessarily remain consistent when evaluated in in vitro and in vivo settings." (PMID 40315226, 2025). "However, neither CD38‐EVs nor EVs effectively accumulated at the tumour site." (PMID 40317915, 2025). "Finally, the inhibitory interaction of CD38 on the stimulator of interferon genes (STING) shown in MM, although less defined, adds a layer of complexity to possible immune modulation and therapeutic responses also in pBL, influencing tumor immune evasion and treatment effectiveness." (PMID 39364393, 2024). "In addition, CD38 serves as a critical initial enzyme in the conversion of NAD+ to ADP-ribose and cyclic ADPR (cADPR), leading to a downstream production of adenosine via the alternative adenosine-generating pathway creating an immune-suppressed tumor microenvironment (TME; 7, 9)." (PMID 39207194, 2024). "However, the mechanism behind the increase in CD38 expression in tumor cells is not yet clear." (PMID 38545257, 2024). "Furthermore, CD38 in hypoxic tumor environment takes partial responsibility for the formation of adenosine, while extracellular adenosine binds to adenosine receptors on CD8+ T cells, thus restraining CD8+ T cell activation and recruiting Tregs to further increase immune resistance in tumor cells." (PMID 38685033, 2024). "Indeed, we could demonstrate that ISB 2001 was able to induce killing of tumor cells from the bone marrow of patients with MM at different concentrations, whereas the control molecules lacking either the anti-CD38 or the anti-BCMA binding domain could not." (PMID 39261676, 2024). "Furthermore, it can activate NK cells in the absence of CD38-positive target tumor cells." (PMID 36834545, 2023). "Similarly, tumor PCs (CD19hetCD20hetCD27hetCD38+CD45loCD138+) preferentially showed an increase in expression of B cell marker CD20 and mIg (IgA, IgG, and IgM) in premalignant stages, with downregulation of several markers including CD19, CD27, CD38, and CD45 in both NDMM and RRMM." (PMID 36752202, 2023). "Given in vitro data showing CD38 deletion protected NK cells from DARA-induced fratricide, we hypothesized that both NK cell persistence and cytotoxicity against MM target cells would be augmented in tumor-bearing mice receiving treatment with CD38KO NK cells and DARA." (PMID 35135865, 2022). "However, CD8+ T cells expressing CD38 in the tumor microenvironment still have strong cytokine secretion and tumor-killing ability, partly due to the high expression of CD103 in CD38+ CD8+ T cells, which helps to increase the resident capacity of immune cells in tumor tissues." (PMID 35906622, 2022). "Investigations in larger numbers of anti-CD38 antibody-treated patients may provide further evidence on the changes occurring among immune effectors within the tumor microenvironment of responders and non-responders, as well as insights on their relevance for selection of subsequent treatment." (PMID 35943588, 2022).
tumor (continued). "To explore the role of tumor-infiltrating CD38+ CD8+ T cells in NSCLC and whether they can be used as target cells for immunotherapy, we investigated the prognostic value, functional characteristics and response to anti-PD-1 antibody of CD38+ CD8+ T cell subsets in vitro." (PMID 33934206, 2021). "Similarly, the proportion of CD38+ TAMs was not altered after the addition of anti-CSF-1R in both tumor types in comparison with the original IT, and the number of Egr2+ TAMs only marginally decreased after the addition of anti-CSF-1R into treated mice with TC-1/A9 tumors." (PMID 34205330, 2021). "However, it is possible that we may not have completely excluded CD38 expression on cells within the tumor microenvironment, such as T cells, macrophages and dendritic cells." (PMID 33629216, 2021). "However, biodistribution and tumor suppression studies established CD38-targeted nanoparticles to have significantly increased in vivo tumor accumulation, tumor cell uptake, and tumor suppression over both nontargeted and CD138-targeted nanoparticles due to the latter’s poor selectivity." (PMID 33138841, 2020). "A potential obstacle to CD38's use as an MM target is its expression on T cells; however, a preclinical study has shown that T cell fratricide does not preclude the efficacy of anti-CD38 BsAbs as long as tumor cells are lysed at a higher or equal rate to T cells." (PMID 32391000, 2020). "However, when the target antigen is not entirely MM-cell specific, such is the case with CD38 or SlamF7, increasing the affinity of (bispecific) antibodies or CAR T-cells may increase the risk of off-tumor toxicity." (PMID 32316450, 2020). "In order to determine whether antibodies bound to CD38 could influence DTT-mediated denaturation of CD38, we incubated CD38-expressing tumor cells with 5 mM DTT and NAD+, in the presence or absence of daratumumab or hcAb MU1067 and analyzed the reaction products by HPLC." (PMID 33396591, 2020). "Nevertheless, because our data clearly demonstrate that CD203a is not expressed on gene and protein level, we hypothesize that independent of a potential CD38 expression, the adenosinergic non-canonical pathway cannot function in the tumor to produce AMP to fuel CD73." (PMID 33194619, 2020). "Furthermore, we could show a high CD38 expression within primary EAC, which was recently determined to be influenced by CD8 + T-cells within the tumor microenviroment and consequently correlates with the tumor inflammation signature." (PMID 31960110, 2020). "Lapidot and colleagues found that only the population of leukaemic cells that were positive for CD34 and negative for CD38 (CD34+CD38−) could initiate leukaemic engraftment in immune-deficient mice, and that the frequency of these tumour-initiating cells was about one per million cancer cells." (PMID 29991569, 2018). "Thus, tumor cells often express pan B-cell markers (cluster of differentiation 19 [CD19], CD29, CD79a) and in 90% of cases express BCL-6 and MUM1, whereas plasma cell-associated proteins such as CD38 and CD138 are usually absent." (PMID 30446015, 2018). "However, a number of anti-tumor antibodies target molecules expressed by tumor cells belonging to the hematopoietic lineage and, hence, also target their normal cell counterparts, notably lymphocytes (anti-CD20, -CD52, -CD38, SLAMF7, etc.)and myeloid cells (anti-CD30, -CD33, etc.)." (PMID 28855903, 2017). "Daratumumab also shows preclinical anti‐tumor activity against CD38‐expressing CLL tumor cells and inhibits adhesion and migration of CLL tumor cells in the tumor microenvironment 133, 134, indicating that CD38‐targeting antibodies may also be of value in the treatment of CD38‐positive CLL." (PMID 26864107, 2016). "Specifically, three BARs recognizing distinct, non-overlapping epitopes on human CD38 induced dose- and time-dependent CDC against tumor cell lines in vitro." (PMID 41254160, 2025).